STX5 (syntaxin 5)
Description:
Mediates endoplasmic reticulum to Golgi transport. Together with p115/USO1 and GM130/GOLGA2, involved in vesicle tethering and fusion at the cis-Golgi membrane to maintain the stacked and inter-connected structure of the Golgi apparatus. [Isoform 2]: Required for Golgi to endoplasmic reticulum retrogade transport, and for intra-Golgi transport. (Microbial infection) Required for the efficient production of infectious virion during human cytomegalovirus infection. Mechanistically, participates in the formation of the cytoplasmic viral assembly compartment where tegument acquisition and envelopment occur.
Synonyms: STX5A; SED5; CDG2AA
Tractability: Antibody: UniProt predicts a signal peptide or a membrane-spanning region. PROTAC: ubiquitination databases record sites on it; its protein half-life has been measured.
Gene: Protein-coding gene on chromosome 11 (62,806,860 to 62,832,051, reverse strand). Ensembl gene ENSG00000162236.
Subcellular location: Endoplasmic reticulum-Golgi intermediate compartment membrane; Golgi apparatus membrane
Subcellular location (Human Protein Atlas): Golgi apparatus; Nucleoplasm
Pathways (Reactome):
Vesicle-mediated transport: COPI-mediated anterograde transport; COPII-mediated vesicle transport; Cargo concentration in the ER; Intra-Golgi traffic
Signal Transduction: RHOA GTPase cycle; RHOC GTPase cycle; RHOG GTPase cycle
Protein localization: Insertion of tail-anchored proteins into the endoplasmic reticulum membrane
Gene Ontology:
Molecular function: cadherin binding; protein binding; SNAP receptor activity; SNARE binding
Biological process: early endosome to Golgi transport; Golgi disassembly; positive regulation of protein catabolic process; regulation of Golgi organization; retrograde transport, endosome to Golgi; endoplasmic reticulum to Golgi vesicle-mediated transport; Golgi organization; Golgi vesicle transport; intercellular transport; intracellular protein transport; membrane fusion; vesicle-mediated transport
Cellular component: Golgi apparatus; Golgi membrane; vesicle; cytosol; endoplasmic reticulum membrane; endoplasmic reticulum-Golgi intermediate compartment membrane; ER to Golgi transport vesicle membrane; SNARE complex; bounding membrane of organelle; membrane
Genetic constraint (gnomAD): Loss-of-function variants: 15 observed, 42.04 expected, observed/expected ratio (o/e) 0.36, 90% interval 0.24 to 0.55. The upper end of that interval is the gene's LOEUF score, 0.55, which puts it in group 2 of 6, group 1 being the genes least tolerant of losing a copy. Missense variants: 430 observed, 441 expected, observed/expected ratio (o/e) 0.98, 90% interval 0.9 to 1.06. Synonymous variants: 184 observed, 163.46 expected, observed/expected ratio (o/e) 1.13, 90% interval 1 to 1.27.
Homologues: Orthologues: macaque STX5 (99% identical), chimpanzee STX5 (99% identical), pig STX5 (98% identical), dog STX5 (98% identical), rat Stx5 (95% identical), mouse Stx5a (94% identical), guinea pig STX5 (91% identical), tropical clawed frog stx5 (78% identical), zebrafish stx5a (69% identical), zebrafish stx5al (65% identical), Drosophila melanogaster Syx5 (53% identical), Caenorhabditis elegans syx-5 (39% identical). Paralogues in human: STX1A (23% identical), STX1B (22% identical), STX2 (22% identical), STX3 (22% identical), STX4 (21% identical), STX16 (17% identical), STX12 (16% identical), STX7 (15% identical), STX11 (14% identical), STX19 (14% identical), TSNARE1 (14% identical), STX17 (12% identical).
Diseases named in the same sentence as STX5 in open-access papers:
STX5 is named in the same sentence as 14 diseases in open-access papers, as found by Europe PMC text mining. Sharing a sentence is not in itself a finding about the gene and the disease. The quoted sentences say what the papers report.
endometriosis (3 papers, 2015 to 2023). The growth of functional endometrial tissue in anatomic sites outside the uterine body. "They concluded that the blood serum levels of syntaxin-5 were significantly increased in the endometriosis group, compared to the control group." (PMID 32143439, 2020). "Furthermore, serum levels of syntaxin-5 in stage I and II endometriosis were found to have different levels compared to controls." (PMID 32143439, 2020). "Additionally, serum anti-PDIK1L and anti-syntaxin 5 autoantibodies were reported elevated in endometriosis patients." (PMID 26240814, 2015). "With the use of the panel of six biomarkers proposed for early diagnosis of endometriosis, the sensitivity increased to 79% and specificity to 80%, and these parameters exceeded those of serum CA 19-9 (43% and 48%), α-enolase (36% and 80%), and syntaxin 5 (38% and 80%)." (PMID 37958566, 2023).
asthma (1 paper, 2020). "They include RBM42, STX5, and TRIM41 in asthma, CYP27A1, GM2A, LGALS9, SPI1, and NLRC4 in COPD, as well as ATF3, PPP1R15A, ZFP36, SOCS3, NAMPT, and GADD45B in IPF." (PMID 31952466, 2020). "These genes included RBM42, STX5, and TRIM41 in asthma, CYP27A1, GM2A, LGALS9, SPI1, and NLRC4 in COPD, ATF3, PPP1R15A, ZFP36, SOCS3, NAMPT, and GADD45B in IPF, LRRC48 and CETN2 in asthma-COPD, COL15A1, GIMAP6, and JAM2 in asthma-IPF and LMO7, TSPAN13, LAMA3, and ANXA3 in COPD-IPF." (PMID 31952466, 2020). "According to the results, RBM42, STX5, and TRIM41 may have critical functions in asthma." (PMID 31952466, 2020).
congenital disorder of glycosylation (1 paper, 2025). Congenital disorder of glycosylation (CDG) is a fast growing group of inborn errors of metabolism characterized by defective activity of enzymes that participate in glycosylation (modification of proteins and other macromolecules by adding and processing of oligosaccharide side chains). "Congenital disorder of glycosylation (CDG) has been linked to clinical cases with deficient CAML and Stx5 short form (Stx5S)." (PMID 39823474, 2025).
HCMV infection (1 paper, 2022). "Examples include the Golgi residents syntaxin 5 (STX5) and Golgi reassembly stacking protein 65 kD (GRASP65), ER chaperone BiP, and nuclear WDR5 that translocates to the vAC during HCMV infection." (PMID 36506089, 2022).
hepatocellular carcinoma (1 paper, 2024). A malignant tumor that arises from hepatocytes. "Moreover, STX5 has been recently described to modulate PI3K/mTOR pathway activation, subsequently restraining cell adhesion and thus favoring metastasis in hepatocellular carcinoma." (PMID 38564289, 2024).
lymphoma (1 paper, 2025). A malignant (clonal) proliferation of B- lymphocytes or T- lymphocytes which involves the lymph nodes, bone marrow and/or extranodal sites. "Moreover, Beclin 2 interacts with STX5 to promote the fusion of ATG9A-mediated vesicles with autophagosomes, degrading MEKK3 and thus suppressing the development of lymphoma." (PMID 39735677, 2025).
parasite (1 paper, 2017). "In additional studies, a small compound called Retro-2 that had been shown to block retrograde transport by disrupting Stx5, was shown to limit parasite infections in vivo and in macrophages where it reduced the aggrandizement of LPVs that harbored parasites of the L. mexicana complex." (PMID 28505157, 2017).
Parkinson disease (1 paper, 2019). A progressive degenerative disorder of the central nervous system characterized by loss of dopamine producing neurons in the substantia nigra and the presence of Lewy bodies in the substantia nigra and locus coeruleus. "Both in Alzheimer’s and Parkinson’s disease, Stx5 has been implicated." (PMID 31357511, 2019). "Stx5 may also play a role in Parkinson’s disease, as a disease-related mutant of α-synuclein (A53T) binds to Stx5 and GosR2, and this reduces the formation of the Stx5-GosR2-Bet1-Sec22b SNARE complex, thereby possibly impairing ER-Golgi transport." (PMID 31357511, 2019).
infection (4 papers, 2018 to 2021). The state of being infected such as from the introduction of a foreign agent such as serum, vaccine, antigenic substance or organism. "Second, Stx5 is required for infection with adeno-associated virus (AAV), although here, it is likely responsible for viral transport from endosomes to the trans-Golgi network." (PMID 31357511, 2019). "Insight into the function of Stx5 is important given its essential role in the secretory pathway of eukaryotic cells and its involvement in infections and neurodegenerative diseases." (PMID 31357511, 2019). "First, infection with human cytomegalovirus (HCMV) results in increased cellular levels of Stx5, which is recruited to the viral assembly site and is required for the efficient production of viral particles." (PMID 31357511, 2019). "Stx5 is involved in neurodegenerative diseases and infections of intracellular parasites and viruses." (PMID 31357511, 2019). "Infection of Asna1Panc−/− pancreatic explants with Asna1 wild-type construct partly restored acinar cell differentiation as well as Stx5 expression in the Golgi." (PMID 29180572, 2018).
nervous system diseases (1 paper, 2022). "Among genes of module-3, NAPA showed the strongest association (60%), SCFD1, and STX5(30–40%) suggesting their possible role in the etiology of nervous system diseases." (PMID 34918006, 2022).
neurodegenerative disease (1 paper, 2019). A disorder of the central nervous system characterized by gradual and progressive loss of neural tissue and neurologic function. "Moreover, Stx5 is tightly regulated during cell division and is hijacked by several pathogens to promote their replication within infected cells, and dysregulation of Stx5-mediated trafficking is implicated in neurodegenerative diseases." (PMID 31357511, 2019).
STX5 also shares sentences with these, for which no sentence is quoted: tumor (2 papers); cancer (1); disorder of glycosylation (1).